FOSL2 (FOS like 2, AP-1 transcription factor subunit)
Diseases named in the same sentence as FOSL2 in open-access papers (continued):
Sharing a sentence is not in itself a finding about the gene and the disease.
Corneal opacity (2 papers, 2023 to 2025). A reduction of corneal clarity. "The identified variant associated with corneal opacity, together with the expression pattern, indicated an important function of FOSL2 in the cornea." (PMID 37856539, 2023). "In this study, we have found a predicted-pathogenic heterozygous missense variant in FOSL2 in a proband with corneal opacity." (PMID 37856539, 2023). "PAX6, FOXC1, and p63 are known to be associated with corneal opacity, and FOSL2 is a novel corneal opacity gene identified in this study." (PMID 37856539, 2023). "We identified FOSL2 as a shared epithelial and novel TF associated with corneal opacity, which was corroborated by in vitro and in vivo protein expression." (PMID 37856539, 2023). "Importantly, we showed that the key TFs and their target genes that drive the LSC-specific epithelial program are associated with corneal diseases and identified a novel disease candidate FOSL2 associated with corneal opacity." (PMID 37856539, 2023). "Fos like 2 (FOSL2) is considered a target gene of PAX6 and is closely associated with corneal opacity." (PMID 40828815, 2025). "FOSL2 is regarded as a downstream gene regulated by PAX6 and has been closely linked to corneal opacity." (PMID 40828815, 2025). "To further assess the function of FOSL2 in LSCs and corneal opacity, we performed siRNA knockdown of FOSL2 in primary LSCs." (PMID 37856539, 2023). "Importantly, we discovered that FOSL2, a direct PAX6 target gene, is a novel candidate associated with corneal opacity, and it regulates genes implicated in corneal diseases." (PMID 37856539, 2023). "Furthermore, we provided evidence for potential TFs and regulatory mechanisms in corneal diseases by uncovering a novel role for FOSL2 in corneal opacity." (PMID 37856539, 2023). "Therefore, deregulation of tight junction genes and up-regulation of pro-angiogenic genes upon FOSL2 knockdown strongly support FOSL2 relevance in LSCs identity and the corneal opacity phenotype, as well as the skin phenotype in reported patients." (PMID 37856539, 2023).
Ewing sarcoma (2 papers, 2022 to 2024). A small round cell tumor that lacks morphologic, immunohistochemical, and electron microscopic evidence of neuroectodermal differentiation. "A notable exception was that Fosl2, which was recently identified as a suppressor of Ewing sarcoma cell growth, was upregulated by EWS-FLI1 knockdown in both cell lines." (PMID 39201282, 2024). "Second, the direct regulating mechanism of FOSL2-PHLDA1-FOXC1-TNFA signaling via NFkB in Ewing sarcoma is unclear." (PMID 36092920, 2022). "Signal axis, FOSL2-PHLDA1-FOXC1-TNFA signaling via NFkB, is first reported to be associated with tumorigenesis and progression of Ewing sarcoma." (PMID 36092920, 2022). "Importantly, signal axis FOSL2-PHLDA1-FOXC1-TNFA signaling via NFkB was extracted for the subsequent analyses by theoretical basis and literature review, which will be explained in detail in the following sections as potential mechanism related to the tumorigenesis of Ewing sarcoma." (PMID 36092920, 2022).
Infertility (2 papers, 2026). "In vivo studies using conditional Fosl2 knockout demonstrated a complete halt in FSH-dependent follicle maturation and resultant infertility." (PMID 41955481, 2026).
lymphoma (2 papers, 2018 to 2023). A malignant (clonal) proliferation of B- lymphocytes or T- lymphocytes which involves the lymph nodes, bone marrow and/or extranodal sites. "We detected a significant enrichment of c-FOS, FOSL1, FOSL2, c-JUN, and BATF target genes in H3K27ac ChIP–seq peaks upregulated in ITK–SYK+PD-1− lymphoma cells compared to their premalignant ITK–SYK+PD-1+ counterparts." (PMID 37723306, 2023).
osteoarthritis (2 papers, 2023 to 2024). A noninflammatory degenerative joint disease occurring chiefly in older persons, characterized by degeneration of the articular cartilage, hypertrophy of bone at the margins and changes in the synovial membrane. "FOSL2 has been demonstrated to regulate the formation of inflammasomes, directly associating with osteoarthritis chondrocytes." (PMID 39376659, 2024). "As inflammatory activity is critical to the pathogenesis of osteoarthritis, determining whether the FOSL2 regulon contributed to osteoarthritis-associated inflammation via IL-6, or other immunity-related genes, warrants further study." (PMID 36793138, 2023). "Firstly, the identified APDEGs—MARCKS, ZFAND5, BCL6, FOSL2, ELL2, and SGCD—may provide deeper insights into osteoarthritis pathogenesis." (PMID 39376659, 2024).
T-cell leukemia (2 papers, 2022). A malignant disease of the T-lymphocytes in the bone marrow, thymus, and/or blood. "In adult T-cell leukemia, aberrantly expressed FOSL2 has been demonstrated to induce CCR4 expression MDM2." (PMID 36092920, 2022).
bone metabolism disorders (1 paper, 2023). "Functional state changes of CREM, FOSL2, FOXC2, RUNX2, and CREB3L1 regulons regarding immunity, cell proliferation, and differentiation identified the important cell stages or subtypes that may be predominantly affected by bone metabolism disorders." (PMID 36793138, 2023).
brain tumors (1 paper, 2023). "We then evaluated the expression of SOX2 and FOSL2 in different subtypes of lung and brain tumors." (PMID 36932385, 2023).
breast adenocarcinoma (1 paper, 2019). "Given that it has been shown by others that FOSL2 is also a target of miR-597-5p in breast adenocarcinoma, the objective of the current work was to determine whether FOSL2 is regulated by miR-597-5p in CRC and the role of miR-597-5p in CRC." (PMID 31245295, 2019).
cardiac hypertrophy (1 paper, 2021). "In the angiotensin II-mediated cardiac hypertrophy model, hearts isolated from Ccl19CreAtg5flox/flox mice were not only protected from increased collagen content, but also showed less gp38-expressing and Fosl-2-expressing fibroblasts and αSMA-positive myofibroblasts in comparison to controls." (PMID 33668422, 2021). "Using a cardiac hypertrophy model induced by continuous infusion of angiotensin II with osmotic minipumps, we confirmed that mice lacking either Fosl-2 (Ccl19CreFosl2flox/flox) or Atg5 (Ccl19CreAtg5flox/flox) in stromal cells were protected from cardiac fibrosis." (PMID 33668422, 2021).
corneal diseases (1 paper, 2023). "To further explore the association of FOSL2 with corneal diseases, we questioned whether the target genes of FOSL2 are enriched for corneal disease genes, similar to other known LSC TFs such as PAX6, FOXC1, and p63." (PMID 37856539, 2023). "FOSL1, along with FOSL2, a novel candidate for corneal disease in our study, and other TFs from the FOS and JUN families, are known to be important in epidermal cells." (PMID 37856539, 2023). "With this method, we identified that the genes associated to our “curated corneal disease list” were significantly more likely to be bound by PAX6, FOXC1, RUNX1, and FOSL2." (PMID 37856539, 2023). "Overall, our analysis highlighted that FOSL2 and several other key LSC TFs binding is enriched in the TSS regions of cornea disease genes, suggesting that they directly regulate cornea disease genes." (PMID 37856539, 2023).
COVID-19 (1 paper, 2024). A disease caused by infection with severe acute respiratory syndrome coronavirus 2. "For example, individuals with moderate COVID-19 demonstrated lower levels of FOSL2, MAX, MAFB, IRF1, RUNX3, and HIF1A in CD14 and CD16 monocytes from other cohorts." (PMID 39712003, 2024). "In agreement with previous studies, we also highlighted the elevation of ATF3, CEBPB, FOSL2, and MITF with COVID-19 severity." (PMID 39712003, 2024). "Moreover, we identified that more than half of the Mon IFI30 marker peaks were shared with monocytes from infants affected with COVID-19, and BACH1, NFE2L2, FOS, and FOSL2 are the master regulators of the cell state." (PMID 39712003, 2024).
Dyskinesia (1 paper, 2015). A movement disorder which consists of effects including diminished voluntary movements and the presence of involuntary movements. "Downregulation of HNF4A has been reported in blood from PD patients as a PD biomarker correlating with motor symptoms severity, whereas FOSL2 has been linked to dyskinesia, a major side effect in the DA substitutive treatment with L‐DOPA." (PMID 26516212, 2015).
focal glomerular sclerosis (1 paper, 2019). "FOSL1 and FOSL2 are also members of the FOS gene family and overexpressed in various renal diseases like IgAN, lupus nephropathy, and focal glomerular sclerosis, with pivotal roles in glomerular sclerosis and mesangial proliferation." (PMID 31392215, 2019).
heart failure (1 paper, 2020). Inability of the heart to pump blood at an adequate rate to meet tissue metabolic requirements. "Microarray results also revealed common induction of transcription factor-coding genes whose modulation in response to CPB has not been described, among which IER2, IER3, and FOSL2 play critical role in cardiac remodeling and apopotosis, myocardial dysfunction, and heart failure." (PMID 31924244, 2020).
hematoma (1 paper, 2024). A hematoma is a collection of blood from a vascular structure into an extravascular space. "Regulating the expression of FOSL2 (Fos-related antigen 2) may favor inflammation inhibition and hematoma resolution in intracerebral hemorrhage." (PMID 39684322, 2024).
Hepatic fibrosis (1 paper, 2022). The presence of excessive fibrous connective tissue in the liver. "Hepatic fibrosis, which is important risk factor in the prognosis of NAFLD patients is related not only to traditional TGF-β pathway, but also FOSL2, ADAM17, and angiotensin pathway." (PMID 36405611, 2022).
keloid (1 paper, 2025). An irregularly shaped, elevated mark on the skin caused by deposits of excessive amounts of collagen during wound healing. "By predicting the major TFs upstream of the identified SE-associated genes, it was discovered that FOSL2, BACH2, and FOXP1 were not only highly enriched in keloid fibroblasts but also significantly upregulated in keloids." (PMID 40702440, 2025). "We also found that FOSL2, BACH2, and FOXP1 were significantly highly expressed in the keloid group, and the results were as shown in the heatmap." (PMID 40702440, 2025). "By utilizing keloid sample data for TF analysis and target gene prediction, we identified three potential master TFs (FOXP1, FOSL2, and BACH2) that may regulate the expression of these five SE-associated genes in keloids." (PMID 40702440, 2025).
keratoconus (1 paper, 2023). A degenerative, structural disorder of the eye, characterized by a cone-shaped protrusion of the cornea. "This is in line with the reported link between keratoconus and down-regulation of FOSL1, an AP1 complex partner of FOSL2." (PMID 37856539, 2023).
knee osteoarthritis (1 paper, 2024). "Specifically, cinnamaldehyde may affect knee osteoarthritis by regulating apoptosis-related genes such as ZFAND5, BCL6, ELL2, FOSL2, MARCKS, and SGCD." (PMID 39376659, 2024).
metastatic cancer (1 paper, 2022). A carcinoma which has spread from the original site of growth to another anatomic site. "Earlier studies have documented a crucial role of FOSL2 overexpression in metastatic cancer progression across multiple cancer subtypes owing to its influence on cell migration and proliferation." (PMID 35805190, 2022).
Myocardial fibrosis (1 paper, 2023). "The role of the transcription factor Fosl-2 in promoting myocardial fibrosis, arrhythmias and aberrant response to stress under immunofibrotic conditions is described using an in vivo mouse model and human cardiac fibroblasts." (PMID 36759717, 2023). "Fosl-2 overexpression in non-inflammatory conditions was not able to induce myocardial fibrosis and affect cardiac electrophysiology." (PMID 36759717, 2023).
nasopharyngeal carcinoma (1 paper, 2020). A carcinoma arising from the nasopharyngeal epithelium. "The lncRNA AFAP1‐AS1 competitively inhibits miR‐423‐5p expression in nasopharyngeal carcinoma cells to regulate the Rho/Rac pathway, thereby mediating the expression of FOSL2 and ultimately, promoting the distant metastasis of nasopharyngeal carcinoma cells." (PMID 33174687, 2020).
neuroblastoma (1 paper, 2015). Neuroblastoma (NB) is the most common solid, extracranial childhood tumor. "To validate these predictions we performed track discovery and found as first ranked track the ChIP-seq of FOSL2, an AP-1 family member, obtained from the neuroblastoma SK-N-SH cell line, strongly indicating that the predicted regions are bona fide AP-1-binding sites." (PMID 25865119, 2015).
Obesity (1 paper, 2023). Accumulation of substantial excess body fat. "TGFB1 and FOSL2 are both major transcription factors and closely related to the pathological process of obesity in PCOS." (PMID 36873932, 2023).
osteoporosis (1 paper, 2016). A condition of reduced bone mass, with decreased cortical thickness and a decrease in the number and size of the trabeculae of cancellous bone (but normal chemical composition), resulting in increased fracture incidence. "Longitudinal studies are needed to clarify the methylation state of FOSL2 among osteoporosis and T2DM with osteoporosis patients; it is worthwhile to investigate whether FOSL2 promotes the formation of osteoblasts and the role of FOSL2 in this and other metabolic diseases." (PMID 28050569, 2016).
pancreatitis (1 paper, 2023). Inflammation of the pancreas. "We observed a steady increase in the expression of FOXP3, LRRC32, as well as FOSL2 and IL6 from normal through pancreatitis to PAAD." (PMID 36932385, 2023).
Parkinson disease (1 paper, 2024). A progressive degenerative disorder of the central nervous system characterized by loss of dopamine producing neurons in the substantia nigra and the presence of Lewy bodies in the substantia nigra and locus coeruleus. "The DisGeNET database labels NLRP1, MSC, PTK2B, TAC1 and FOSL2 as genes associated with Parkinson’s disease, with association scores of 0.964, 0.944, 0.907, 0.889 and 0.888, respectively." (PMID 38350848, 2024).
preeclampsia (1 paper, 2021). Preeclampsia is a hypertensive disorder of pregnancy that is characterized by new-onset hypertension with proteinuria presenting after 20 weeks of gestation, and depending on mild or severe forms may initially present with severe headache, visual disturbances, and hyperreflexia. "Meanwhile, we found that FOSL2 was downregulated in preeclampsia (PE) by analyzing the transcriptome of PE, which was ascribed to decreased angiogenesis signaling." (PMID 33754039, 2021).
renal fibrosis (1 paper, 2023). A final common manifestation of a wide variety of chronic kidney diseases characterized by glomerulosclerosis and tubulointerstitial fibrosis. "This study aimed to clarify the role and underlying mechanisms of FOSL2 in renal fibrosis." (PMID 37662889, 2023). "In summary, our data established a functional role for FOSL2 in the progression of renal fibrosis." (PMID 37662889, 2023). "Fos-related antigen 2 (FOSL2) plays a facilitative role in fibrotic disease; however, its role in renal fibrosis remains unclear." (PMID 37662889, 2023). "Bioinformatics analysis revealed that serum/glucocorticoid regulated kinase 1 (SGK1) may be regulated by FOSL2 and involved in renal fibrosis." (PMID 37662889, 2023). "We further examined the functional role of FOSL2 in renal fibrosis in vivo and in vitro." (PMID 37662889, 2023). "Notably, we also found that FOSL2 knockdown repressed the activation of SGK1 transcription, suggesting that the FOSL2/SGK1 axis plays an important role in TGF-β1–mediated pathological effects on renal fibrosis." (PMID 37662889, 2023). "Gene Ontology (GO) function and Kyoto Encyclopedia of Genes and Genomes (KEGG) pathway enrichment analysis based on these upregulated genes indicated that FOSL2 might participate in the development of renal fibrosis." (PMID 37662889, 2023). "Thus, the FOSL2/SGK1 axis may be a novel target for molecular-targeted therapies for renal fibrosis." (PMID 37662889, 2023). "Thus, the FOSL2/SGK1 axis may serve as a potential therapeutic target for inhibiting the development of renal fibrosis." (PMID 37662889, 2023). "The role of FOSL2 in renal fibrosis and its potential as a therapeutic target have not yet been investigated." (PMID 37662889, 2023). "FOSL2 plays an essential role in promoting renal fibrosis in an SGK1-dependent manner, and targeting the FOSL2/SGK1 signaling axis may offer a potential strategy for the treatment of renal fibrosis." (PMID 37662889, 2023). "Therefore, the FOSL2/SGK1 profibrotic axis may be a promising biomarker and therapeutic target for renal fibrosis." (PMID 37662889, 2023).
rheumatoid arthritis (1 paper, 2025). A chronic, systemic autoimmune disorder characterized by inflammation in the synovial membranes and articular surfaces. "Additionally, VEGFA was implicated in the Rheumatoid arthritis process, while FOSL2 was associated with Osteoclast differentiation." (PMID 40997129, 2025).
sarcoma (1 paper, 2025). A usually aggressive malignant neoplasm of the soft tissue or bone. "Several of the FET-sarcoma-specific and shared transcription factors formed a protein interaction network, with MLS-specific JUN, RUNX1, FOSL2, and CREB5 as center nodes." (PMID 40988026, 2025).
serous ovarian cancer (1 paper, 2022). "Accordingly, overexpression of some acting on genes like FOSL2, NFIB, NFIC, and PROCR, which are associated with proliferation and metastasis, predicts poor prognosis in high-grade serous ovarian cancer." (PMID 35935940, 2022).
Shock (1 paper, 2020). The state in which profound and widespread reduction of effective tissue perfusion leads first to reversible, and then if prolonged, to irreversible cellular injury. "It is also associated with FOSL2 in pediatric septic shock and LILRB2 and ITGAM in pediatric resolved SIRS." (PMID 32318053, 2020).
skin squamous cell carcinoma (1 paper, 2022). A carcinoma arising from the squamous cells of the epidermis. "Furthermore, circRNA_001937 expression in skin squamous cell carcinoma is increased, and silencing its expression may inhibit the progression of this disease by regulating the miRNA-597-3p/FOSL2 pathway." (PMID 35543347, 2022).
small cell lung carcinoma (1 paper, 2021). Small cell lung cancer (SCLC) is a highly aggressive malignant neoplasm, accounting for 10-15% of lung cancer cases, characterized byrapid growth, and early metastasis. "KEGG analysis showed that the function of FOSL2 was mainly enriched in the neuroactive ligand-receptor signaling pathway, Nod-like receptor signaling, ECM receptor interaction, small cell lung cancer, and focal adhesion, suggesting that FOSL2 may play a role in LUAD through these pathways." (PMID 35003395, 2021). "The functions of FOSL2 are mainly related to neuroactive ligand-receptor interaction, nod-like receptor signaling pathway, ECM receptor interaction, small cell lung cancer, and focal adhesion." (PMID 35003395, 2021).
steatosis (1 paper, 2021). Increased lipid within the cytoplasm of cells. "NAMPT, PHLDA1, RALGDS, GADD45B, and FOSL2 were all in the brown module, with a lower expression for steatosis and NASH samples and with a higher expression for normal samples." (PMID 34041361, 2021).
thyroid cancer (1 paper, 2021). "This not only suggests that post-translational regulation may affect activity of FOSL2 in thyroid cancer but also indicates that our footprinting approach likely detects functional TF–chromatin interactions." (PMID 34593797, 2021).